RPS8 (ribosomal protein S8)
Description:
Component of the small ribosomal subunit. The ribosome is a large ribonucleoprotein complex responsible for the synthesis of proteins in the cell. Part of the small subunit (SSU) processome, first precursor of the small eukaryotic ribosomal subunit. During the assembly of the SSU processome in the nucleolus, many ribosome biogenesis factors, an RNA chaperone and ribosomal proteins associate with the nascent pre-rRNA and work in concert to generate RNA folding, modifications, rearrangements and cleavage as well as targeted degradation of pre-ribosomal RNA by the RNA exosome.
Synonyms: S8; eS8
Tractability: Small molecule: an approved drug acts on it; a structure with a bound ligand is known; a high-quality ligand is known. PROTAC: UniProt records ubiquitination sites on it; ubiquitination databases record sites on it; its protein half-life has been measured; a small molecule that binds it is known. Other modalities: a drug acting on it is in phase 2 or 3 trials.
Target class: Other cytosolic protein
Gene: Protein-coding gene on chromosome 1 (44,775,251 to 44,778,779, forward strand). Ensembl gene ENSG00000142937.
Subcellular location: Cytoplasm; Membrane; Nucleus, nucleolus
Subcellular location (Human Protein Atlas): Cytosol; Endoplasmic reticulum
Pathways (Reactome):
Metabolism of proteins: Eukaryotic Translation Termination; Formation of a pool of free 40S subunits; Formation of the ternary complex, and subsequently, the 43S complex; GTP hydrolysis and joining of the 60S ribosomal subunit; L13a-mediated translational silencing of Ceruloplasmin expression; PELO:HBS1L and ABCE1 dissociate a ribosome on a non-stop mRNA; Peptide chain elongation; Ribosomal scanning and start codon recognition; SRP-dependent cotranslational protein targeting to membrane; Translation initiation complex formation; ZNF598 and the Ribosome-associated Quality Trigger (RQT) complex dissociate a ribosome stalled on a no-go mRNA
Disease: SARS-CoV-1 modulates host translation machinery; SARS-CoV-2 modulates host translation machinery; Viral mRNA Translation
Metabolism of RNA: Major pathway of rRNA processing in the nucleolus and cytosol; Nonsense Mediated Decay (NMD) enhanced by the Exon Junction Complex (EJC); Nonsense Mediated Decay (NMD) independent of the Exon Junction Complex (EJC)
Cellular responses to stimuli: Response of EIF2AK4 (GCN2) to amino acid deficiency
Developmental Biology: Regulation of expression of SLITs and ROBOs
Metabolism: Selenocysteine synthesis
Gene Ontology:
Molecular function: protein binding; RNA binding; structural constituent of ribosome
Biological process: ribosomal small subunit biogenesis; cytoplasmic translation; translation
Cellular component: cytoplasm; cytosol; cytosolic ribosome; cytosolic small ribosomal subunit; endoplasmic reticulum; extracellular exosome; focal adhesion; membrane; nucleus; ribonucleoprotein complex; small-subunit processome; nucleoplasm; nucleolus; ribosome
Genetic constraint (gnomAD): Loss-of-function variants: 0 observed, 28.61 expected, observed/expected ratio (o/e) 0, 90% interval 0 to 0.1. The upper end of that interval is the gene's LOEUF score, 0.1, which puts it in group 1 of 6, group 1 being the genes least tolerant of losing a copy. Missense variants: 138 observed, 263.51 expected, observed/expected ratio (o/e) 0.52, 90% interval 0.46 to 0.6. Synonymous variants: 96 observed, 97.03 expected, observed/expected ratio (o/e) 0.99, 90% interval 0.84 to 1.17.
Homologues: Orthologues: guinea pig RPS8 (100% identical), macaque RPS8 (100% identical), mouse Rps8 (100% identical), pig RPS8 (100% identical), rat Rps8 (100% identical), dog RPS8 (99% identical), tropical clawed frog rps8 (95% identical), zebrafish rps8a (93% identical), zebrafish rps8b (92% identical), Drosophila melanogaster RpS8 (70% identical), Caenorhabditis elegans rps-8 (68% identical).
Diseases named in the same sentence as RPS8 in open-access papers:
RPS8 is named in the same sentence as 22 diseases in open-access papers, as found by Europe PMC text mining. Sharing a sentence is not in itself a finding about the gene and the disease. The quoted sentences say what the papers report.
pancreatic cancer (5 papers, 2018 to 2025). "Previous studies have reported that the mRNA expression level of RPS8 was elevated in pancreatic cancer tissues and associated with poor prognosis." (PMID 37274336, 2023). "RPS8 overexpression is associated with short survival times in pancreatic cancer patients compared with the ones who express a lower level of RPS8." (PMID 34873618, 2021). "Furthermore, Chen and colleagues found that PRELP, LGALS1 and RPS8 might be significant prognostic factors for pancreatic cancer, while another study showed that PNMA1 was associated with prolonged overall survival and might serve as a prognostic biomarker for pancreatic cancer." (PMID 29515771, 2018). "RPS8, RPL15 and RPL21 could also serve as biomarkers in pancreatic cancer." (PMID 34873618, 2021).
colorectal cancer (4 papers, 2017 to 2022). A primary or metastatic malignant neoplasm that affects the colon or rectum. "Increased expression of ribosomal protein genes including rpS3, rpS6, rpS8, rpS12 and rpL5 has been reported in colorectal cancer." (PMID 32973493, 2020). "In colorectal cancer, the elevation of some specific small RPs, including RPS3, RPS6, RPS8, and RPS12, increases ribosome biogenesis and possibly leads to the activation of extra-ribosomal functions such as DNA replication, RNA splicing and modification, and cell growth." (PMID 35159381, 2022). "For example, the expression of RPL5, RPS3, RPS6, RPS8, and RPS12 in colorectal cancer was higher than that in normal colorectal mucosa." (PMID 33584809, 2020).
COVID-19 (4 papers, 2022 to 2023). A disease caused by infection with severe acute respiratory syndrome coronavirus 2. "The optimal 24 feature genes, which were further analyzed by consulting the retrieved literature, we found that four genes (XAF1, OAS2, CES1, RPS8) have been reported in COVID-19." (PMID 35812523, 2022). "Through unbiased KEGG pathway analysis of DEGs between Fga−/− and WT plasma-stimulated microglia, we identified the 12 top pathways induced by fibrinogen, including ROS (for example, Hmox1, Cox7a2, Slc25a5), COVID-19 (for example, Ccl12, Rps8, Rpl35) and AD (for example, Atp5e, Psmd2, Tubb5)." (PMID 37291385, 2023).
hepatocellular carcinoma (2 papers, 2020 to 2024). A malignant tumor that arises from hepatocytes. "The mRNA level of RPS8, RPL12, RPL23A, RPL27, and RPL30 was detected as upregulated in hepatocellular carcinoma tissues and cell lines." (PMID 33584809, 2020).
virus infection (2 papers, 2015 to 2023). "Currently, limited information is available on the functional relationship between RPS8 and virus infection." (PMID 38140603, 2023). "However, the function of RPS8 in the virus infection of plants remains unclear." (PMID 38140603, 2023). "However, the function of RPS8 in virus infection in plants has not been reported." (PMID 38140603, 2023).
Alzheimer disease (1 paper, 2024). A progressive, neurodegenerative disease characterized by loss of function and death of nerve cells in several areas of the brain leading to loss of cognitive function such as memory and language. "Notably, six of these proteins (RPS3A, RPS4X, RPS8, RPS14, RPS20 and RPL31) were upregulated in brain capillaries of Alzheimer’s disease patients." (PMID 38732249, 2024).
babesiosis (1 paper, 2019). Babesiosis refers to a condition caused by microscopic parasites that infect the red blood cells. "RPS8 has been used to develop a species-specific PCR-RFLP diagnostic tool for ovine babesiosis and theileriosis, which are hemoprotozoal diseases that cause economic losses among sheep and goats in tropical and subtropical regions." (PMID 30891061, 2019).
ependymoma (1 paper, 2023). A WHO grade II, slow growing tumor of children and young adults, usually located intraventricularly. "Therefore, we focused on comparing the overlapping clusters between normal and tumor and identified tumor-specific genes such as CASC15 and microRNA MIR99AHG in neuron-like ependymomas and RPS14 and RPS8 in glia-like ependymomas." (PMID 37095395, 2023).
liver cancer (1 paper, 2023). An epithelial or non-epithelial malignant neoplasm that arises from the liver. "The results demonstrated that the expression of FCER1G, PFN1, ACTG1, PABPC1, CALM1, and RPS8 was significantly upregulated in the liver cancer cells, whereas KLRB1, LDB2, and FYN exhibited the opposite trend." (PMID 37397471, 2023).
systemic lupus erythematosus (1 paper, 2019). An autoimmune multi-organ disease typically associated with vasculopathy and autoantibody production. "In skin, there were four core-ASE genes, including TNXB, which is related to the pathogenesis of systemic lupus erythematosus and RPS8, which is involved in resistance to hemoprotozoal diseases that cause economic losses among sheep and goats in tropical and subtropical regions." (PMID 30891061, 2019).
testicular cancer (1 paper, 2021). A primary or metastatic malignant neoplasm that affects the testis. "Among 25 hub genes, EFTUD2, HNRNPD, KIT, NCL and RPS8 were significantly upregulated in testicular cancer patients, however, ELAVL2 and NRXN1 were significantly downregulated using GEPIA online database." (PMID 33746583, 2021). "As expected, EFTUD2, ELAVL2, HNRNPD, KIT, NCL, NRXN1 and RPS8 were significantly varied in testicular cancer patients." (PMID 33746583, 2021).
tumor (11 papers, 2016 to 2026). "Increased expression of various ribosomal proteins (rpS8, rpL12, rpL23a, rpL27, and rpL30) have been associated with tumor growth." (PMID 32973493, 2020). "RPS8 was mainly involved in protein folding and stability, and in tumor studies, RPS8 has the potential to serve as a biomarker specific to tumors due to its tendency for elevated expression levels in tumor tissues and cells compared to normal tissues." (PMID 39691708, 2024). "RPS8 (40S ribosomal protein S8; component of the ribosomal 40S subunit) participates in tumor development as a rate-limiting factor during translational control." (PMID 33856140, 2021). "In addition, RPS8 was highly expressed in alcohol-associated HCC and associated with tumor progression, thus serving as a potential biomarker and therapeutic target for alcohol-associated HCC." (PMID 37274336, 2023). "We found that RPS8 was up-regulated in tumor tissues (FC = 1.4)." (PMID 27631501, 2016).
cancer (6 papers, 2017 to 2024). A tumor composed of atypical neoplastic, often pleomorphic cells that invade other tissues. "Consistent with our KEGG analysis, the downregulation of several genes that encode protein components of the ribosome (RPL8, RPS8, and RPL10A) in plasma is associated with cancer." (PMID 35816095, 2022). "Interestingly, several of these proteins are also known to be important in MYC-driven cancers like ribosome components (such as Rps8), multiple subunits of the eukaryotic translation initiation factor 3 complex, and proteins important for MYC-induced autophagy (such as Atg3)." (PMID 38302473, 2024).
infection (3 papers, 2012 to 2022). The state of being infected such as from the introduction of a foreign agent such as serum, vaccine, antigenic substance or organism. "This allele is expressed during infection but differs by two amino acids from Avr3a45C (K64P and A65S), a change that could possibly explain the differential responses of Rps3a and Rps8 towards its gene product." (PMID 35150190, 2022). "The time of sample analysis was 48 hours post infection which would represent up to 16 half lives for the 40S ribosomal protein S8 which would result in the effective complete disappearance of this protein." (PMID 22514668, 2012).
RPS8 also shares sentences with these, for which no sentence is quoted: breast carcinoma (1 paper); colorectal tumors (1); lung adenocarcinoma (1); osteosarcoma (1); prostate carcinoma (1); Sepsis (1); tauopathies (1); theileriosis (1).